PIK3CA (phosphatidylinositol-4,5-bisphosphate 3-kinase catalytic subunit alpha)
Diseases named in the same sentence as PIK3CA in open-access papers (continued):
Sharing a sentence is not in itself a finding about the gene and the disease.
cancer (continued). "The PI3K/PTEN/AKT/mTORC1 pathway is often deregulated in human cancers due to mutations at PI3K (PIK3CA), PTEN, AKT, MTOR and tuberous sclerosis complex 2 (TSC2)." (PMID 33917370, 2021). "BYL719 (Alpelisib), which works as a selective PI3Kα inhibitor, is a treatment for PIK3CA-associated cancers." (PMID 34074347, 2021). "Mutations in PIK3CA are associated with higher rates of mutations in other genes of important cancer-associated pathways such as the tyrosine kinase receptors/K-Ras/BRAF/MAPK and the Wnt/β catenin pathway." (PMID 33435133, 2021). "In this regard, we and others have shown that many PIK3CA-associated cancers harbour multiple independent mutations activating the PI3K pathway, including multiple PIK3CA mutations in cis or trans." (PMID 34762647, 2021). "PIK3CA is another gene frequently mutated/altered in human cancers and, by dictating expression of the catalytic subunit of PI3K, contributes significantly to a number of cellular pathways that regulate cell growth, motility, metabolism and survival." (PMID 34283054, 2021). "In the phase III trial SOLAR-1, alpelisib improved the PFS in the cohort with PIK3CA-mutated cancer (11.7 months in the alpelisib-fulvestrant group versus 5.7 months in the placebo-fulvestrant group)." (PMID 34885105, 2021). "Although numerous PIK3CA-activating variants have been identified in cancer, three mutational hotspots are characterized by strong oncogenic activity: p.His1047Arg, p.Glu542Lys, and p.Glu545Lys account for 80% of the spectrum." (PMID 34944785, 2021). "Overexpression of wild-type Pik3ca or the hotspot Pik3caH1047R mutation has been linked to dedifferentiation and stemness in murine models of cancer, particularly of the breast, but Pik3ca gene dose-dependent regulation was not addressed in these studies." (PMID 34762647, 2021). "The PIK3CA mutation has been reported to be associated with improved recurrence-free survival and cancer-specific survival in patients with BLCA." (PMID 33732281, 2021). "PIK3CA is the second most frequently mutated gene in cancers and is extensively studied for its role in promoting cancer cell resistance to chemotherapy or targeted therapy." (PMID 33827485, 2021). "The PIK3CA gene, encoding the p110α subunit, is frequently mutated or amplified in the most common human cancers, including those of the breast, colon, gastric, endometrial, cervical, prostate, and lung, as well as glioblastoma." (PMID 33572326, 2021). "PIK3CA gene variants were associated with improved recurrence-free survival and improved cancer-specific survival in patients with UC treated with radical cystectomy." (PMID 34851968, 2021). "We estimate KRAS is mutated in only 11% of all cancers, which is less than PIK3CA (13%) and marginally higher than BRAF (8%)." (PMID 34645806, 2021).
cancer (continued). "And 13 APOBEC-related associations were observed in BLCA (n = 9), BRCA (n = 2), and CESC (n = 2), of which p.E542K and p.E545K in PIK3CA accounted for 46.2% (6/13) associations across three cancer types." (PMID 34901014, 2021). "PIK3CA mutations are common in multiple human cancers, including colon (32%), brain (27%), stomach (25%), breast (8%), and lung (4%) cancer." (PMID 35008235, 2021). "PIK3CA mutations are observed frequently in a broad spectrum of cancers, including the most prevalent cancers such as breast, endometrial, and colorectal cancers." (PMID 33435133, 2021). "The HMOsisEC10 KRAS and HMOsisEC10 PIK3CA mutant cell lines in our study were insufficient, despite having driver mutations and aggressive behavior, to induce cancer development." (PMID 34202354, 2021). "To conclude, further studies are needed to confirm the potential role of PIK3CA mosaicism in cancer susceptibility." (PMID 34075207, 2021). "The PI3K/AKT pathway was shown to be activated in human cancers by oncogenic mutations of the PIK3CA gene encoding the catalytic subunit p110a." (PMID 34926293, 2021). "We recently reported that human PSCs with two endogenous alleles of the strongly activating cancer hotspot mutation PIK3CAH1047R exhibit pronounced phenotypic differences compared to isogenic cells heterozygous for the same PIK3CA variant." (PMID 34762647, 2021). "Among the 7 putative cancer-associated genes at 3q26 listed in OncoKB database, only PIK3CA is frequently mutated in squamous cervical carcinomas in 32.4% of cases, while the other genes are rarely mutated in 3.2% or fewer cases." (PMID 34436017, 2021). "The core component genes of the pathway CTNNB1, encoding for β catenin, APC and CDH1, encoding for E cadherin, are less frequently mutated, but also their prevalence is higher in PIK3CA mutated cancers than wild-type ones." (PMID 33435133, 2021). "For example, it has been shown that both, PTEN loss and PIK3CA mutation can lead to the activation of the PI3K or MAPK pathway in cancer of the breast, colorectum, stomach or lung." (PMID 35251119, 2021). "PIK3CA-mutated preclinical cancer models are sensitive to PI3K inhibitors, which appear to function synergistically with endocrine therapies." (PMID 34020697, 2021). "The repertoire of postzygotic PIK3CA pathogenic variants in PROS is identical to that in cancer, and so repurposing of candidate anticancer drugs targeted at PI3K is an obvious strategy." (PMID 34385668, 2021). "AS below 4 is observed in 30.3% mutated cancers compared to 15.9% of PIK3CA wild-type squamous cervical carcinomas." (PMID 33435133, 2021). "In particular, our group and others have recently reported the clonal expansion of cancer-associated mutations such as PIK3CA, KRAS, and PTEN in histologically normal endometrial glands using single gland sequencing or laser capture microdissection." (PMID 34442357, 2021). "Numerous somatic mutations, including cancer-associated mutations in ARID1A, ATM, CDH4, NRAS, and PIK3CA, were shared among the epithelium from the uterine endometrium, endometriotic lesions distant from and adjacent to the carcinoma, and the carcinoma itself." (PMID 33809880, 2021). "A sensitive and quantitative allele‐specific PCR approach (ACB‐PCR) was used to measure PIK3CA H1047R mutation in normal breast tissues from cancer‐free individuals, focusing on this mutation because it is the most prevalent hCDM detected in breast carcinomas." (PMID 31469467, 2020). "The mutation in PIK3CA observed in TK-RIG915 occurs at a cancer-associated hotspot known to upregulate kinase activity." (PMID 33053751, 2020).
cancer (continued). "More studies to explore the clinical superiority of PI3K inhibitors are warranted in HR+/PIK3CA-mutated breast cancer and other cancer forms." (PMID 32461963, 2020). "PIK3CA mutated cancers had longer TTM compared to wild type tumors (HR = 0.73 95% CI 0.55–0.95 p = 0.022)." (PMID 32326897, 2020). "Mutations in the p110alpha subunit (PIK3CA) are associated with anti-cancer drug resistance, aggressive histologic features, and poor overall survival." (PMID 33096795, 2020). "A seminal study in the field of MpBC research found that this rare cancer type harbors ~ 47% PIK3CA mutations and ~ 5% PTEN deletions." (PMID 33148288, 2020). "Activating mutations of class I PI3Ks, mainly of PIK3CA, the gene encoding the catalytic subunit p110α, have been found in several cancer types along with copy number gains or amplification of class I PI3Ks and alteration of the regulatory subunits." (PMID 33003448, 2020). "Our panel included cancer cell lines with activating PIK3CA mutations, inactivating PTEN mutations, AKT gene amplification or amplification of either ERBB2 or MET (both of which have been previously shown to be associated with AKT dependence)." (PMID 32439931, 2020). "All of these PIK3CA mutations have been described previously in human cancers, and most have been characterized as activating oncogenic mutations." (PMID 32210430, 2020). "In the sub-analysis performance of each cancer type, the cancer types with higher PIK3CA mutation rates showed better AUPRs." (PMID 33166334, 2020). "In particular, oncogenic mutations in the gene encoding the p110α catalytic subunit, PIK3CA, occur with high frequency in several common cancers." (PMID 32844214, 2020). "PIK3CA is one of the most frequently mutated genes in human cancers and its somatic mutations have also been reported in lung cancer." (PMID 33273537, 2020). "The cancer phenotype of MCF10ACA1a was further promoted due to a subsequent activating PIK3CA H1047R mutation." (PMID 32830861, 2020). "In multiple cancer types, including breast cancer, PIK3CA is considered oncogenic, mutations of the alpha catalytic subunit of PI3K having an incidence of 40% in ER+/HER2− primary and metastatic tumors." (PMID 33375317, 2020). "In many cancers, Pik3ca, the gene encoding P110α, is often mutated, which increases kinase activity and leads to varying PTEN and EGFR expression." (PMID 31952518, 2020). "Upon inspection of the genes most frequently A3-mutated in HPV-associated cancers, the PIK3CA proto-oncogene is almost exclusively mutated at two helical domain hotpots." (PMID 33292100, 2020). "The PIK3CA protein is a prominent oncogene in many types of cancers with functions linked to cell survival and proliferation." (PMID 32498309, 2020). "Twenty-three tumors' genomic mutations were investigated; PIK3CA had mutated in 5 of 6 T2 or more deeply invasive cancers, of which, 4 were located in the proximal colon." (PMID 33031197, 2020). "Because PIK3CA mutation prevalence varied across cancer types, the performance of each cancer type was investigated." (PMID 33166334, 2020). "The PIK3CA mutation trials are based on epidemiological data that aspirin after a diagnosis of CRC is most effective if the cancer has a PIK3CA mutation." (PMID 32153653, 2020). "The PIK3CA p.E81K mutation is also a known hotspot mutation in cancer and is recurrently identified in an inherited disease (PIK3CA-related overgrowth spectrum)." (PMID 32235312, 2020).
cancer (continued). "Activating mutations in PIK3CA, the gene encoding the catalytic p110α subunit of PI3Kα, are also considered disease-drivers in human cancers as well as developmental overgrowth disorders known as PROS (PIK3CA-related overgrowth spectrum)." (PMID 32010943, 2020). "Mutations in these same hotspot regions of PIK3CA are also found in cancer, developmental tissue overgrowth syndromes termed PIK3CA-Related Overgrowth Spectrum (PROS), and simple lymphatic and venous malformations." (PMID 32350708, 2020). "For example, the His1047Arg substitution derives from A→G at location 3:178952085 (GRCh37/hg19) in the driver gene PIK3CA and has been implicated in various cancers." (PMID 32282885, 2020). "PI3K consists of a regulatory (p85) subunit and a catalytic (p110) subunit; the latter one is encoded by 3 genes including PIK3CA, PIK3CB, and PIK3CD, and the PIK3CA mutation is the most frequent in cancers." (PMID 32908885, 2020). "For cancer patients with known KRAS or PIK3CA mutations (as determined by tissue testing) we also compared the presence of oncogenic mutations in plasma and urine samples." (PMID 32251424, 2020). "PIK3CA mutations, associated with many distinct cancers, include hotspot single–amino acid substitutions in the helical (E542K and E545K) or kinase (H1047R) domains." (PMID 33375317, 2020). "The sensitivity of cancer cells to drugs can often be compromised by PIK3CA, Ras and BRAF mutations." (PMID 33371382, 2020). "It is known that mutations in PIK3CA are related to a variety of human cancers, and the mutant PIK3CA is considered an oncogene." (PMID 33117683, 2020). "Mutations in PIK3CA are commonly found in solid human cancers and also in benign overgrowth syndromes known collectively as PIK3CA-related overgrowth spectrum (PROS)." (PMID 32677674, 2020). "In our methods, we collect the responsive and survival data according to the PIK3CA mutation status in ctDNA analysis, which is broadly applied to detect the gene mutation status in cancers." (PMID 32461963, 2020). "In this study, we isolated EC populations from CLVM patients and identified cancer-associated hotspot PIK3CA mutations in EC from 7/7 patients." (PMID 32350708, 2020). "The PIK3CA mutation activates many downstream pathways that regulate critical cellular functions involved in the development of cancer." (PMID 33054840, 2020). "It has been demonstrated that the primary molecular mechanisms regulating PIK3CA overexpression in cancer were mutation and amplification." (PMID 33344221, 2020). "Despite the presence of the same somatic activating PIK3CA mutations identified in cancer, PROS and CLVM rarely acquire a malignant phenotype." (PMID 32350708, 2020). "Previous studies in HNSCC as well as in other cancers that harbor activating mutations in PIK3CA have found these genetic alterations only targetable to a limited extent." (PMID 33036331, 2020). "In particular, activating mutations in PIK3CA, the gene encoding the catalytic subunit of PI3Kα, are among the most common across multiple human cancer types and are also the cause of benign yet highly debilitating developmental overgrowth disorders." (PMID 32010943, 2020). "Expression of the most frequently occurring PIK3CA cancer hotspot variant, H1047R, has been linked to dedifferentiation and stemness in mouse models of breast, lung and colorectal cancers." (PMID 32010943, 2020). "This is consistent with cancer cells harbouring oncogenic PIK3CA mutations exhibiting enhanced dependency on RNMT." (PMID 30991934, 2019). "The most common cancer-associated alterations in the PI3K pathway are activating mutations in PIK3CA which encodes p110α." (PMID 31018529, 2019).
cancer (continued). "Of note, somatically acquired mutations of PIK3CA are reported in many cancers, including breast (MIM 114480), colorectal (MIM 114500), gastric (MIM 613659), hepatocellular (MIM 114550) and ovarian (MIM 167000)." (PMID 31413155, 2019). "PIK3CA is one of the most commonly mutated oncogenes in several types of human cancer, including breast, colon and endometrial cancer." (PMID 31404155, 2019). "The p110α encoding gene PIK3CA is one of the most frequently mutated genes in most human cancers, especially breast, ovarian and colorectal cancers." (PMID 31461863, 2019). "In contrast to the complex genetics of cancer, activating PIK3CA mutations arise heterozygously and in isolation in the severe overgrowth disorders known as PROS." (PMID 30948643, 2019). "Deregulation of genes involved in the PI3K pathway, including mutations of the PI3K catalytic subunit alpha (PIK3CA) and loss of Pten, is frequently found in cancer." (PMID 30975125, 2019). "Of the three isoforms belonging to this class of kinases, PIK3CA is the only gene ubiquitously expressed and frequently mutated in human cancer." (PMID 30999672, 2019). "Alterations in the PIK3R1 gene are less common than PIK3CA mutations with an average of 3% across all cancer types." (PMID 30650664, 2019). "In particular, since this study determined the HLA-restriction and precise epitope sequences in PIK3CA-H1047R or C-Kit-D816V, we will confirm their immunogenicity in T cells from HLA-matched cancer patients with the corresponding mutations in a future study." (PMID 30813491, 2019). "Somatic variants along the entire length of PIK3CA have been identified in various cancers, including many of the same hotspot P/LP variants observed in PROS." (PMID 30761771, 2019). "For instance, mutations of PIK3CA reprogramme metabolism and are associated with poorer survival outcomes in several cancers, including those of the colon, rectum, breast and lungs." (PMID 31754644, 2019). "About 11, 26, and 10.5% of diffuse-type C-I, C-II, and intestinal-type GCs exhibited PIK3CA mutations in TCGA cohort, and the overall responsive rate was reported 35% for cancer patients with PIK3CA mutations treated with PI3K/AKT/mTOR pathway inhibitors." (PMID 30866995, 2019). "PIK3CA, which encodes the catalytic subunit of phosphatidylinositol 3-kinase α (PI3Kα), is mutated in a wide variety of human cancers including ~30% of CRCs8." (PMID 31844152, 2019). "Genetic analysis of PIK3CA-associated cancers revealed that 64% had multiple oncogenic PIK3CA copies (39%) or additional PI3K signaling pathway-activating “hits” (25%)." (PMID 30948643, 2019). "Several experimental studies have indicated that cancers with PIK3CA/PTEN mutations are sensitive to everolimus; however, clinical trials did not draw the same conclusions." (PMID 31088410, 2019). "PIK3CA mutations are considered driver mutations that provide transformative and positive advantages for cancer cells growing mainly in clear-cell, endometroid, and mucinous OvCa." (PMID 31284467, 2019). "On the other hand, the more selective PI3K inhibitors, such as alpelisib and taselisib, featured promising results, in particular, in PIK3CA-mutated cancer patients." (PMID 31450618, 2019). "The commonest PIK3CA “hot-spot” variant, H1047R, has been studied extensively in cancer models, both in cells and in vivo." (PMID 30948643, 2019). "Many data reveal that the somatic gene of phosphoinositide-3-kinase-catalytic-alpha (PIK3CA) result mutated in several human cancer such as HCC." (PMID 31766556, 2019).